Y_RNA (Y RNA )
Gene: Miscellaneous RNA gene on chromosome 19 (52,259,076 to 52,259,187, reverse strand). Ensembl gene ENSG00000207265.
Homologues: Orthologues: chimpanzee Y_RNA (98% identical). Paralogues in human: RNY1P5 (87% identical), Y_RNA (86% identical), Y_RNA (85% identical), Y_RNA (84% identical), Y_RNA (83% identical), Y_RNA (82% identical), RNY1 (81% identical), Y_RNA (81% identical), RNY1P1 (80% identical), RNY1P6 (80% identical), Y_RNA (80% identical), RNY1P14 (79% identical), and 96 more.